CSRNP1 (cysteine and serine rich nuclear protein 1)
Description:
Binds to the consensus sequence 5'-AGAGTG-3' and has transcriptional activator activity (By similarity). May have a tumor-suppressor function. May play a role in apoptosis.
Synonyms: CSRNP-1; TAIP-3; AXUD1; URAX1; DKFZp566F164; FAM130B
Tractability: PROTAC: ubiquitination databases record sites on it.
Gene: Protein-coding gene on chromosome 3 (39,141,854 to 39,154,852, reverse strand). Ensembl gene ENSG00000144655.
Subcellular location: Nucleus
Subcellular location (Human Protein Atlas): Nucleoplasm; Vesicles
Gene Ontology:
Molecular function: protein binding; DNA-binding transcription factor activity; DNA-binding transcription factor activity, RNA polymerase II-specific; sequence-specific DNA binding; DNA-binding transcription activator activity, RNA polymerase II-specific
Biological process: apoptotic process; positive regulation of transcription by RNA polymerase II; regulation of transcription by RNA polymerase II
Cellular component: nucleoplasm; chromatin; nucleus
Genetic constraint (gnomAD): Loss-of-function variants: 8 observed, 23.51 expected, observed/expected ratio (o/e) 0.34, 90% interval 0.2 to 0.61. The upper end of that interval is the gene's LOEUF score, 0.61, which puts it in group 2 of 6, group 1 being the genes least tolerant of losing a copy. Missense variants: 649 observed, 739.12 expected, observed/expected ratio (o/e) 0.88, 90% interval 0.82 to 0.94. Synonymous variants: 283 observed, 286.86 expected, observed/expected ratio (o/e) 0.99, 90% interval 0.89 to 1.09.
Homologues: Orthologues: chimpanzee CSRNP1 (99% identical), macaque CSRNP1 (97% identical), pig CSRNP1 (85% identical), dog CSRNP1 (83% identical), rabbit CSRNP1 (79% identical), guinea pig CSRNP1 (78% identical), mouse Csrnp1 (74% identical), rat Csrnp1 (72% identical), tropical clawed frog csrnp1 (44% identical), zebrafish csrnp1b (41% identical), zebrafish csrnp1a (33% identical), Drosophila melanogaster Axud1 (28% identical), and 1 more. Paralogues in human: CSRNP3 (33% identical), CSRNP2 (29% identical).
Diseases named in the same sentence as CSRNP1 in open-access papers:
CSRNP1 is named in the same sentence as 19 diseases in open-access papers, as found by Europe PMC text mining. Sharing a sentence is not in itself a finding about the gene and the disease. The quoted sentences say what the papers report.
colon carcinoma (5 papers, 2007 to 2021). "Interleukin-2 induces CSRNP1 (also known as Axin1 upregulated 1; AXUD1) in mouse T cells; it expresses a 1.7 kb transcript with five exons in some malignant cancers, such as kidney, liver, lung, and colon carcinomas." (PMID 33869003, 2021). "Axin-upregulated 1 (Axud1)/Cystein-serin-rich nuclear protein 1 (Csrnp1) is a putative tumor suppressor gene that is upregulated by exogenous Axin1 expression in a colon cancer cell line." (PMID 19732418, 2009). "The ortholog of CSRNP-1, AXUD1, was previously identified as a gene that is up-regulated by over-expression of AXIN1 in a human colon cancer cell line." (PMID 17726538, 2007).
hepatocellular carcinoma (2 papers, 2023 to 2025). A malignant tumor that arises from hepatocytes. "To investigate the functional role of CSRNP1 in hepatocellular carcinoma, we evaluated the effects of its knockdown on cell proliferation, migration, and invasion." (PMID 41502527, 2025).
hypoxic-ischemic encephalopathy (2 papers, 2022 to 2024). "Furthermore, Csrnp1 is highly associated with hypoxic-ischemic encephalopathy, according to RNA sequencing." (PMID 36203804, 2022). "CSRNP1 has only been identified as a key gene associated with neonatal hypoxic-ischemia brain damage by RNA sequencing and single-nucleotide polymorphism screening, and also a candidate target for hypoxic-ischemic encephalopathy therapy, but lacks further investigations." (PMID 38902590, 2024). "More recently, studies have identified that CSRNP1 was one of the most relevant genes to organ injuries including hypoxic-ischemic encephalopathy and non-alcoholic fatty liver disease (NAFLD) via sequencing and bioinformatic strategies, but lack of further investigation." (PMID 38902590, 2024).
breast carcinoma (1 paper, 2007). "Conversely, AXUD1/CSRNP-1 has been shown to be down-regulated in microarray studies in a variety of tumors including lung, liver, colon and kidney cancers, intrahepatic cholangiocarcinomas, pancreatic tumors and breast cancers." (PMID 17726538, 2007).
cholangiocarcinoma (1 paper, 2021). A carcinoma that arises from the intrahepatic biliary tree (intrahepatic cholangiocarcinoma) or from the junction, or adjacent to the junction, of the right and left hepatic ducts (hilar cholangiocarcinoma). "Among the 20 upregulated transcription factors, CEBPD, CSRNP1, and KLF10 were regularly underexpressed in cholangiocarcinoma but upregulated by PDT treatment." (PMID 34805140, 2021).
tuberculosis (1 paper, 2022). A chronic, recurrent infection caused by the bacterium Mycobacterium tuberculosis. "Furthermore, we validated the accuracy of some differentially expressed genes in an independent cohort using quantitative PCR, and obtained three novel genes (RBM3, CSRNP1, SRSF5) with the ability to discriminate active tuberculosis from LTBI and HC." (PMID 36059536, 2022).
tumor (17 papers, 2003 to 2025). "CSRNP1, hypomethylated following seroconversion, encodes for cysteine-serine-rich nuclear protein 1 which through the Wnt signaling pathway has been shown to have a tumor suppressive function." (PMID 28237978, 2017). "Our findings demonstrate that CSRNP1 functions as a tumor suppressor in HCC by regulating the ROS-mediated activation of the JNK/p38 MAPK pathway, leading to mitochondrial dysfunction and apoptosis." (PMID 41502527, 2025). "The lack of IHC data limits the translational relevance of our findings and precludes a spatial assessment of CSRNP1 expression in the tumor microenvironment." (PMID 41502527, 2025). "Follow-up studies using xenograft or orthotopic mouse models are crucial for evaluating the systemic effects of CSRNP1 on tumor growth, apoptosis, and metastasis." (PMID 41502527, 2025). "In conclusion, our findings demonstrate that CSRNP1 functions as a tumor suppressor in HCC, exerting its anti-tumor effects through the ROS-dependent activation of the JNK/p38 MAPK signaling pathway." (PMID 41502527, 2025). "Our attempts to validate the differential expression of ABHD6 and CSRNP1 transcripts with IHC and RT-qPCR was hampered due to the scarcity of N2-stored tumor tissue." (PMID 35159112, 2022). "We have further characterized this regulatory signature by identifying increased E2f5, Erg1 and Csrnp1, molecules with anti-tumor properties, and Prdm1, whose gene product BLIMP-1 is a negative regulator of interferon (IFN) beta signaling." (PMID 26367386, 2015). "A number of studies have identified AXUD1/CSRNP-1 as a gene that is down-regulated in a variety of cancer, thus implicating the gene as a potential tumor suppressor gene, often considered related to reduced apoptosis." (PMID 17726538, 2007). "CSRNP1 is a novel prognostic biomarker and tumor suppressor in HCC." (PMID 41502527, 2025). "CSRNP1 has emerged as a potential tumor suppressor that may influence stress-related signaling; however, its regulatory relationship with the JNK/p38 MAPK pathway in HCC remains to be fully elucidated." (PMID 41502527, 2025). "It is therefore plausible that CSRNP1 may antagonize ERK1/2 signaling as part of its tumor-suppressive function." (PMID 41502527, 2025). "Collectively, these findings point to a potential tumor-suppressive function for CSRNP1 in HCC." (PMID 41502527, 2025). "In contrast, NR4A1 and CSRNP1 exhibited markedly lower expression in the tumor group." (PMID 41502527, 2025). "Other genes with increased expression in anoxic conditions unique to ventricle included Csrnp1, or Axud1, whose function is unknown but may be involved in tumor suppression." (PMID 26147940, 2015). "CSRNP1 is a nuclear protein involved in various biological processes such as transcriptional regulation, DNA repair, and cell proliferation, while its expression was down-regulated in microarray studies of various tumors, suggesting that this gene is a potential tumor suppressor gene." (PMID 38169659, 2023). "Results showed that CSRNP1, MEF2D and EPAS1 are significantly up-regulated in tumor tissues compared with normal tissues." (PMID 30696880, 2019). "When validating these potential targets in patients samples, we found that three targets named CSRNP1, MEF2D and EPAS1 are significantly up-regulated in tumor tissues when compared with normal tissues." (PMID 30696880, 2019). "Furthermore, CSRNP1 and RETN were down-regulated in tumor tissues, but the down-regulation of both predicted a better prognosis." (PMID 36401283, 2022). "CSRNP1 is a key protein of the non-canonical Wnt pathway, and because of its decreased level of expression in tumor tissues it was suggested to serve as a tumor suppressor." (PMID 32849815, 2020).
cancer (10 papers, 2007 to 2025). A tumor composed of atypical neoplastic, often pleomorphic cells that invade other tissues. "Conversely, CSRNP1, RND3, and RCAN1 were significantly downregulated, each linked to anti-proliferative or prognostic roles in cancer." (PMID 41216224, 2025). "CSRNP1 has been described as a tumor suppressor gene, its expression level decreased in several types of cancers." (PMID 27023475, 2016). "However, research into the role of CSRNP1 in cancer, particularly HCC, remains in its early stages and warrants further investigation." (PMID 41502527, 2025). "One gene involved in free radical scavenging, SOD3, was downregulated, whereas the genes associated with cell cycle or cancer, including GADD45B, ID1, KLF10, CSRNP1, and TM4SF1, were upregulated in F. nucleatum-infected GF(P22) cells when compared to F. nucleatum-infected GF(P4) cells." (PMID 29190775, 2017). "While CSRNP1 has been highlighted in HCC and other cancers through bioinformatic analyses, its functional contribution to HCC development has not been well characterized." (PMID 41502527, 2025).
infection (3 papers, 2017 to 2023). The state of being infected such as from the introduction of a foreign agent such as serum, vaccine, antigenic substance or organism. "Among them, eight DEGs (RF00100, NXPH2, SEC61G, GADD45G, TUBAL3, LIPE, CSRNP1, and FAM20A) were shared across different comparison groups after FX0910 infection." (PMID 37982609, 2023). "The IPA network analysis revealed that infection induced aged GF(P22)-specific DEGs were connected to each other and the upregulated genes (Id1, KLF10, GADD45b, and CSRNP1) were all mainly localized in the nucleus." (PMID 29190775, 2017).
cardiac diseases (1 paper, 2022). "As the most dysregulated transcription factor, Csrnp1 was reported to mainly function in tumors or cardiac diseases, but little is known on the role of this gene in VaD." (PMID 36203804, 2022).
CSRNP1 also shares sentences with these, for which no sentence is quoted: Alzheimer disease (1 paper); COVID-19 (1); Epstein-Barr virus infection (1); intrahepatic cholangiocarcinoma (1); kidney cancer (1); lung squamous cell carcinoma (1); melanoma (1); non-alcoholic fatty liver disease (1); prostate carcinoma (1).